SNORD114-16 (small nucleolar RNA, C/D box 114-16)
Synonyms: 14q(II-16)
Gene: Small nucleolar RNA gene on chromosome 14 (100,973,595 to 100,973,664, forward strand). Ensembl gene ENSG00000199914.
Gene Ontology:
Biological process: RNA processing
Cellular component: nucleolus
Homologues: Orthologues: chimpanzee SNORD114-16 (99% identical), macaque SNORD114-16 (91% identical), mouse Gm23736 (71% identical), rat Snord113l1 (67% identical), mouse Gm22981 (66% identical), rat LOC120093391 (63% identical), mouse AF357341 (59% identical), mouse Gm25856 (57% identical), mouse AF357428 (54% identical). Paralogues in human: SNORD114-3 (86% identical), SNORD114-11 (84% identical), SNORD114-13 (84% identical), SNORD114-23 (83% identical), SNORD114-21 (81% identical), SNORD114-9 (81% identical), SNORD114-12 (80% identical), SNORD114-14 (80% identical), SNORD114-15 (80% identical), SNORD114-26 (80% identical), SNORD114-17 (79% identical), SNORD114-22 (79% identical), and 26 more.